INS (insulin)
Diseases named in the same sentence as INS in open-access papers (continued):
Sharing a sentence is not in itself a finding about the gene and the disease.
metabolic syndrome (continued). "Several cross-sectional epidemiologic studies consistently showed that circulating PRL levels positive correlated with increased insulin sensitivity, lower glucose and lipid levels, and lower prevalence of T2D and metabolic syndrome." (PMID 36993818, 2023). "More precisely, there is a significant link between S1P and elements of metabolic syndrome; for example, fasting plasma insulin, total and LDL cholesterol levels, body fat percentage, and waist circumference are well described." (PMID 37834321, 2023). "Evaluated the impact of S. siliquosum on metabolic syndrome parameters, including heart/liver function, plasma biochemistry, glucose/insulin responses, body composition, and gut microbiota composition." (PMID 37445955, 2023). "Whilst TNF-alpha is a recognised potent trigger of inflammation in IBD, it is also believed to play a role in the metabolic syndrome with data suggesting it impairs insulin signalling, leading to insulin-resistant states." (PMID 37227593, 2023). "This condition is associated with low grade inflammation and is often accompanied by dyslipidemia, decreased insulin sensitivity, and cardiovascular disease; collectively known as metabolic syndrome." (PMID 37089425, 2023). "Individuals with a lower diversity of gut microbiota composition show greater weight gain, reduced insulin sensitivity, dyslipidemia, and increased markers of inflammation." (PMID 37894615, 2023). "Improving adiponectin levels is thought to enhance fatty acid combustion and glucose uptake, enhance insulin sensitivity, and improve metabolic syndrome." (PMID 37108217, 2023). "Compared to their healthy counterparts, patients with type 2 diabetes (T2D) can exhibit an altered gut microbiota composition, correlated with detrimental outcomes, including reduced insulin sensitivity, dyslipidemia, and increased markers of inflammation." (PMID 37605183, 2023). "Significantly elevated body mass index, insulin, blood glucose, and dyslipidemia were noted in groups that were chronically exposed to organophosphorus pesticides; dysregulated liver function was also noted, regardless of gender and age." (PMID 36832892, 2023). "This adipokine as an anti-inflammatory peptide treat metabolic syndromes via inducing insulin sensitivity, anti-inflammatory and anti-oxidative effects." (PMID 37488554, 2023). "Diabetic mice (db/db) with loss of hepatic PEPCK1 have an improved ability to regulate glycemia, insulin sensitivity, and dyslipidemia." (PMID 37249651, 2023). "The fasting glucagon to insulin ratio significantly decreased with increasing metabolic syndrome components." (PMID 37762748, 2023). "Activated ECMR also increases expression of proinflammatory adipokines, including tumor necrosis factor-α (TNFα), interleukins (ILs), and monocyte chemoattractant protein-1 (MCP-1) to directly impair insulin metabolic signaling and related metabolic syndrome." (PMID 37610001, 2023). "Insulin use, comorbidities other than dyslipidemia, reduced cardiac function, and medication adherence were comparable among the four groups." (PMID 37375712, 2023). "Accordingly, our aim was to investigate the relationship between the glucagon to insulin ratio and metabolic syndrome in T2DM patients, in order to identify the effect of glucagon on cardiovascular disease." (PMID 37762748, 2023). "Kv1.3 channel regulates the activity of lymphocytes, macrophages, or adipose tissue and its blockade reduces inflammatory cytokine secretion and improves insulin sensitivity in animals with metabolic syndrome and in genetically obese mice." (PMID 34623540, 2023). "At baseline, markers of metabolic syndrome including mean weight, WC, serum Insulin concentration in the metformin cohort were 187 lbs, 41.14 cm and 10.03 mIU/L respectively, and 177.65 lbs, 40.52 cm and 8.02 mIU/L in the placebo cohort." (PMID 37335291, 2023).
metabolic syndrome (continued). "Evidence suggests that these abnormalities can affect key metabolic pathways, including glucose metabolism, lipid metabolism, and insulin signaling, ultimately leading to the development of metabolic syndrome." (PMID 36968196, 2023). "L-carnitine has also been shown to have anti-inflammatory and antioxidant properties, as well as the capability to improve insulin sensitivity, protein nutrition, dyslipidemia, and membrane integrity." (PMID 38082229, 2023). "Fasting and postprandial glucagon concentrations did not significantly differ between the two groups, but the fasting glucagon to insulin ratio was significantly lower in the metabolic syndrome group." (PMID 37762748, 2023). "For example, A. soehngenii L2-7 is being tested as a probiotic to improve insulin sensitivity in metabolic syndrome patients." (PMID 38239921, 2023). "This study provides compelling evidence supporting the notion that insulin resistance in muscles plays a role in the early development of atherogenic dyslipidemia and non-alcoholic fatty liver disease (NAFLD)." (PMID 37755259, 2023). "In the present study, the glucagon to insulin ratio was significantly lower in patients with T2DM who also have metabolic syndrome." (PMID 37762748, 2023). "A phase 1/2 study of 24 metabolic syndrome patients correlated A. soehngenii engraftment with improved peripheral insulin sensitivity." (PMID 38239921, 2023). "According to the latest update (2021) on the pathophysiology and management of metabolic syndrome, it represents a group of metabolic abnormalities, including abdominal obesity, impaired insulin sensitivity, high blood pressure, and atherogenic dyslipidemia." (PMID 37190276, 2023). "The effects of the glucagon to insulin ratio on the presence of metabolic syndrome among patients with DM were analyzed using hierarchical logistic regression." (PMID 37762748, 2023). "Especially, when the circadian Clock component Bmal1 is disrupted, the subsequent endocrine adaptation has an important impact on insulin sensitivity, liver disease, and the metabolic syndrome." (PMID 36838862, 2023). "In a metabolomics study including 5181 participants from the cross-sectional Metabolic Syndrome in Men study, the levels of KYNA and other downstream metabolites weakened insulin secretion and insulin sensitivity but enhanced susceptibility to T2DM." (PMID 37755297, 2023). "A previous study proposed that OA administration reversed dyslipidemia in T2D mice possibly by the suppression of hepatic glucose production instead of inducing insulin secretion or pancreas morphology change." (PMID 37520251, 2023). "Metabolic diseases in adolescence were identified by calculating the pediatric simple metabolic syndrome score (PsiMS), continuous metabolic syndrome score (cMetS), and single-point insulin sensitivity estimator (SPISE) as MetS indices." (PMID 36677058, 2023). "Previous genetic association studies have shown associations between ABCG5/G8 polymorphisms and triglyceride, HDL, and VLDL cholesterol levels, insulin sensitivity, and metabolic syndrome." (PMID 36981027, 2023). "For any given BMI, men with KS have higher truncal fat percentage as compared with controls, and truncal adiposity has been shown to be the major predictor of metabolic syndrome and insulin sensitivity in these patients." (PMID 37010084, 2023). "Impaired insulin metabolism results in dyslipidemia, which is accompanied by increased apoB stability, MTP, and TNFα release." (PMID 37009872, 2023). "In particular, chronic inflammation due to RA alters body composition, insulin sensitivity, and lipid profiles, and these metabolic outcomes lead to a metabolic syndrome that mediates premature atherosclerosis." (PMID 37239666, 2023). "Central obesity, hypertension, atherogenic dyslipidemia, and insulin (INS) resistance are components of the metabolic disease complex known as metabolic syndrome." (PMID 38003691, 2023).
metabolic syndrome (continued). "Specifically, the metabolic syndrome, a concurrence of disturbed glucose and insulin metabolism, overweight and abdominal fat distribution, mild dyslipidemia, and hypertension, is most important because of its association with cardiovascular disease (CVD)." (PMID 37623340, 2023). "Namely, a link has been shown with the following health issues: glucose-insulin metabolism derangement, overweight/obesity, blood pressure alterations, endothelial dysfunction, lipidic profile modifications, and metabolic syndrome." (PMID 37342257, 2023). "In this study, the metabolic syndrome group had a significantly lower glucagon to insulin ratio, and the glucagon to insulin ratio significantly decreased with an increasing number of metabolic syndrome components." (PMID 37762748, 2023). "Numerous studies have demonstrated that gut microbiota influences insulin resistance, dyslipidemia, atherosclerosis, hepatic steatosis, and elevated blood pressure." (PMID 36835291, 2023). "The Single Point Insulin Sensitivity Estimator (SPISE) is a novel surrogate marker for insulin sensitivity and was found comparable to the gold standard clamp test as well as for predicting the Metabolic Syndrome (MetS) in several populations." (PMID 36673133, 2023). "The glucagon to insulin ratio remained a predictor of metabolic syndrome even after adjusting for several factors." (PMID 37762748, 2023). "In a well-characterized cohort of apparently healthy adults, elevated fasting insulin at baseline was found to be an independent determinant over a 5-year period for the future development of the metabolic syndrome." (PMID 36901984, 2023). "IR, characterized by a significant decline in glucose metabolism in response to insulin, is thought to be a contributory factor of chronic hyperglycemia, dyslipidemia, and hypertension." (PMID 37179310, 2023). "Impaired response to insulin is one of the main molecular mechanisms of dyslipidemia in prediabetic and diabetic patients." (PMID 37240676, 2023). "Consistently, our study also concluded that in Chinese dyslipidemia patients, long-term CoQ10 supplementation improved their insulin sensitivity and lipid profile." (PMID 35241098, 2022). "BA improves insulin sensitivity in metabolic syndrome rats, but inhibits insulin/IGF-1 receptor signaling to suppress de novo lipogenesis in HepG2 cells." (PMID 35967806, 2022). "The plasma levels of apoL1 have been reported to be increased in patients with metabolic syndrome, and an in vitro study has demonstrated that the insulin signaling pathway regulates both the synthesis and the secretion of apoL1 in hepatocytes." (PMID 35130909, 2022). "The different impact of specific fat compartments on insulin sensitivity and lipid levels was well described, with excess abdominal VAT imparting a greater risk of metabolic syndrome than excess abdominal SAT." (PMID 35615717, 2022). "Here, we applied a reliable phosphoproteomic approach to Neuro2a (N2a) cells to identify their molecular features under two different insulin-resistant conditions with clinical relevance: inflammation and dyslipidemia." (PMID 35055191, 2022). "Different fibrates have similar effects on dyslipidemia, but subtly differ in their impact on glucose metabolism, insulin resistance, intermittent claudication, and effects on microvascular complications of diabetes mellitus." (PMID 36010645, 2022). "In contrast, whole-body Becn1 haplo-insufficiency reverses ADI-PEG20-mediated reductions in fasting glucose in addition to blocking the effects on insulin tolerance and dyslipidemia." (PMID 37457375, 2022). "By ingestion of resistant starch, cholesterol and triglycerides are reduced, and insulin sensitivity is improved, which can greatly reduce the incidence of metabolic syndrome." (PMID 35899018, 2022). "Metabolic syndrome should be considered as a clinical diagnosis guided by a complex combination of factors, including impaired fat storage, insulin action and pro-inflammatory factors." (PMID 36648872, 2022).
metabolic syndrome (continued). "Inflammatory responses can stimulate the oxidative stress response of adipocytes, affect their biological processes, such as proliferation and differentiation, and insulin sensitivity, and then lead to dyslipidemia and further accumulation of fat." (PMID 35484204, 2022). "It is proposed that Propolis acts through up-regulation of the PPAR-γ in the adipose tissue, which is a therapeutic target in DM, metabolic syndrome, and CVD, and involved in improving insulin sensitivity, inflammation, and dyslipidemia." (PMID 35057819, 2022). "NGAL also plays an important role in metabolic syndrome and glucose homeostasis, regulating insulin secretion by the pancreatic beta cells." (PMID 36145151, 2022). "Differences in myocardial glucose metabolic rate and insulin sensitivity of subjects with T2DM according to metabolic syndrome compared to control subjects." (PMID 35845046, 2022). "In people with T2D and/or metabolic syndrome, TZDs were shown to improve insulin sensitivity, reduce plasma-free fatty acids and triglycerides, and increase high-density cholesterol (HDL-C)." (PMID 35745754, 2022). "Blood levels of adiponectin are low in patients with features of the metabolic syndrome, and treatment with thiazolidinediones (TZDs), which had been used to improve insulin sensitivity, result in increased adiponectin levels." (PMID 35986215, 2022). "In that context, we have previously reported that the OBE-ISR group improves insulin sensitivity and reduces dyslipidemia in growing rats, as well as GLP-1 augmented levels." (PMID 36532542, 2022). "Lean individuals were more sensitive to chronic butyrate intervention than individuals with metabolic syndrome, in which insulin sensitivity remained unchanged post sodium butyrate intervention." (PMID 36687671, 2022). "A well-formulated KD can quickly and effectively lower levels of blood glucose, insulin, and blood pressure—all considered clinically desirable goals in many patients, particularly those with metabolic syndrome." (PMID 35873236, 2022). "For this reason, we decided to explore possible associations between the MD-related mineral profile and the pathogenic hallmarks behind childhood obesity, namely abnormal insulin-mediated carbohydrate metabolism and dyslipidemia." (PMID 36711380, 2022). "Previously we demonstrated that acute exposure to a HFHS diet 1 week before pregnancy and throughout gestation results in glucose intolerance, decreased beta cell numbers and serum insulin levels, as well as dyslipidemia during pregnancy." (PMID 36520818, 2022). "Non-alcoholic fatty liver disease (NAFLD), a metabolic syndrome (MetS) manifested in the liver (Buzzetti, Pinzani & Tsochatzis, 2016), is pathophysiologically related to adipose tissue inflammation and insulin resistance (Tilg, Adolph & Moschen, 2021)." (PMID 35265397, 2022). "This synthesis pathway using sterol regulatory element-binding transcription factor 1 (SREBP-1c) is stimulated by the high insulin and cholesterol levels that accompany the metabolic syndrome." (PMID 35566490, 2022). "Due to the evidence showing that BTLA showed antioxidant traits, inhibited α-glucosidase, improved insulin sensitivity, and reduced oxidative stress in metabolic syndrome rats, we measured this compound (and others) in extracts using HPLC." (PMID 35883721, 2022). "For example, patients with PCOS phenotype A have higher menstrual irregularities, ovarian reserve parameters, BMI, hyperandrogenism (clinical and biochemical), fasting insulin, and dyslipidemia." (PMID 36010645, 2022). "Similar to previous FMT studies, allogenic FMT using metabolic syndrome donors decreases insulin sensitivity in the metabolic syndrome recipient." (PMID 35402293, 2022). "That correlates with a previous study of L-carnitine supplementation in rats with a metabolic syndrome, where Glut4 was up-regulated, and insulin sensitivity was improved." (PMID 36499250, 2022).
metabolic syndrome (continued). "Correlational analyses were performed relating circulating concentrations of IGFBP-1, anthropometric data, and indices of insulin sensitivity and dyslipidemia." (PMID 35586622, 2022). "Conversely, there is evidence that T levels are positively correlated with insulin sensitivity, and men with low T have a threefold higher prevalence of metabolic syndrome than their eugonadal counterparts." (PMID 35898448, 2022). "NADH/NAD+ reductive stress in the liver emerges as the causal mechanism for features of the metabolic syndrome associated with hypomorphic GCKR, such as hepatic insulin resistance and increased triglyceride release." (PMID 34986329, 2022). "IR is often used to explain the causes of dyslipidemia of PCOS, where the impaired ability of insulin to inhibit lipolysis leads to increased mobilization of FFAs." (PMID 36017313, 2022). "Self‐identified later chronotype adults with metabolic syndrome have blunted aortic waveform responses, and greater inflammation with insulin stimulation compared with early counterparts." (PMID 36301720, 2022). "The intervention with IPA reduced the body weight and peripheral fat content; improved insulin resistance, liver lipid deposition, and peripheral blood lipid content; and maintained intestinal homeostasis, thereby improving metabolic syndrome." (PMID 35370963, 2022). "The results of the present study elucidated that administration of β- Caryophyllene significantly improved glycemic status through improving dyslipidemia in a similar way as metformin thereby improved insulin signalling in diabetic rats." (PMID 37693084, 2022). "All together these factors contribute to lower insulin sensitivity and to the development of dyslipidemia." (PMID 36578055, 2022). "In conclusion, this study shows that PA can significantly lower insulin levels, and high-intensity PA still has additional potential benefits for insulin levels, even in the condition of dyslipidemia and hyperuricemia." (PMID 35185617, 2022). "The transition from a metabolically stable condition to an obese and insulin-resistant state is characterized by a vicious loop that includes hyperinsulinemia, inflammation, glucose tolerance, dyslipidemia, IR, and adipose tissue expansion." (PMID 36297569, 2022). "Pathway analysis of putative DEM targets revealed an enrichment in pathways related to metabolic syndrome, inflammatory response, apoptosis and insulin signaling pathways, metabolic derangements, and decreased immunomodulation." (PMID 35903753, 2022). "Multiple preclinical studies showed that chamomile tea, which contains large quantities of apigenin and luteolin, (up to 1.2% of apigenin), decreases metabolic syndrome and improves insulin sensitivity." (PMID 36555392, 2022). "ABHD6 is a lipase involved in endocannabinoid signaling and possibly has other effects in inflammation, metabolic syndromes, and insulin secretion." (PMID 35159112, 2022). "Proinflammatory cytokines act as crucial factors in metabolic syndromes by disrupting insulin signaling." (PMID 36272977, 2022). "Meanwhile, the fasting and the third hour of insulin levels during the IRT significantly increased in the dyslipidemia group (13.67 vs. 12.05, P=0.004) and (44.33 vs.36.48, P=0.033), as well as HOMA-IR (3.05 vs. 2.65, P=0.009)." (PMID 35860700, 2022). "There were more male patients, current smokers, heavy drinkers, patients with lower income, patients with history of dyslipidemia, insulin users, and patients using more than two OHAs in the AP group." (PMID 36428788, 2022). "For example, while those studies included some measures of insulin and glucose, they also revealed separate components related to adiposity, dyslipidemia (but specifically HDL and TG), and BP." (PMID 36042444, 2022). "The results also revealed that the odds of underprescribing GLP-1 RA and SGLT2i were significantly lower in patients with a history of dyslipidemia, retinopathy, or on insulin therapy." (PMID 36408008, 2022).